H19 (H19 imprinted maternally expressed transcript)
Diseases named in the same sentence as H19 in open-access papers (continued):
Sharing a sentence is not in itself a finding about the gene and the disease.
glioblastoma (continued). "In order to test if H19 can bind to EZH2 in glioblastoma cells, we performed RNA immunoprecipitation (RIP) experiments in LN229 cells transfected with a vector encoding a myc-tagged EZH2, (or EGFP as control)." (PMID 29643989, 2018). "We believe that our results can provide a new piece to the complex puzzle of H19 function in glioblastoma." (PMID 29643989, 2018). "Successively, with the aim of establishing an in vitro system where studying the role of H19 in GBM, we checked H19 expression levels in 5 human glioblastoma cell lines by comparing them with a healthy white matter sample." (PMID 29643989, 2018). "We proceeded in our characterization of the role of H19 in glioblastoma cells by investigating if, by modulating H19, we would be able to affect EZH2 binding to promoters of genes known to be epigenetically regulated by PRC2-mediated trimethylation of H3K27." (PMID 29643989, 2018). "H19 is transcribed by RNA polymerase II and dysregulation of H19 is associated with BRC, CRC, GC, Glioblastoma, HCC, HNC, LC and NSCLC." (PMID 30693021, 2018). "Our results point to a role for H19 as a component of an epigenetic regulatory complex in glioblastoma cells." (PMID 29643989, 2018). "The first observations of H19 expression in glioblastoma cells are relatively recent (last five years) and all indicate an oncogenic role of H19 mediated by enhancing migration/invasion, proliferation as well as stemness." (PMID 29643989, 2018). "In this paper, we take a further step in the understanding of the oncogenic role of H19 in glioblastoma." (PMID 29643989, 2018). "We show that H19, endogenously expressed in glioblastoma cells, positively influences their growth and ability to migrate and invade." (PMID 29643989, 2018). "By employing a factor analysis on a SAGE dataset of 12 glioblastoma samples, we show that H19 expression in glioblastoma tissues correlates with that of several genes involved in glioblastoma growth and progression." (PMID 29643989, 2018). "More specifically, we demonstrated that the depletion of H19 in glioblastoma cells is translated into a specific reduction of EZH2 binding and H3K27 trimethylation at the NKD1 promoter, with a consequent increase of Nkd1 levels." (PMID 29643989, 2018). "In the central nervous system (CNS), H19 is overexpressed in glioblastoma tissue and promotes the proliferation, differentiation, migration, and invasion of glioma cells." (PMID 29636074, 2018). "Among them, H19 has a recognized oncogenic role in several types of human tumors and was shown to correlate to some oncogenic aspects of glioblastoma cells." (PMID 29643989, 2018). "This novel mechanism offers a new understanding of how H19 and miRNAs interact to control gene transcription and offers a new view of the oncogenic role of H19 in glioblastomas." (PMID 28327666, 2017). "In a summary, we found that Hif-1α directly promoted H19 expression through binding to the H19 promoter and indirectly through SP1-mediated H19 transcriptional activation under hypoxia in glioblastoma cells." (PMID 28327666, 2017). "Here we report that hypoxia significantly stimulated H19 expression in glioblastoma cell lines, which was related to hypoxia-inducible factors 1α (Hif-1α)." (PMID 28327666, 2017). "The expression of Hif-1α, PTEN and H19 levels were analyzed in 22 human glioblastoma tissues (GBM) and 15 adjacent normal brain tissues (NBT) removed from patients." (PMID 28327666, 2017). "Overexpression of lncRNA H19 promotes metastasis, angiogenesis, and stemness in glioblastoma and cholangiocarcinoma cells through effects on EMT and is associated with poor prognosis." (PMID 28872613, 2017). "In vitro, long noncoding RNA H19 (H19-IRP) promotes glioblastoma multiforme (GBM) immunosuppression by binding to CCL2 and galectin-9 promoters to activate its transcription and recruiting myeloid-derived suppressor cells (MDSCs) and TAMs to induce T cell exhaustion and an immunosuppressive GBM-TME." (PMID 41341593, 2025).
glioblastoma (continued). "LncRNA H19 enhances TMZ resistance in glioblastoma through competitive RNA targeting of BMP2." (PMID 40297808, 2025). "Furthermore, hypoxia has been shown to promote carcinogenic effects in glioblastoma by directly and indirectly inducing H19 expression through hypoxia-inducible transcription factor 1 alpha (HIF-1α ) activity." (PMID 38987833, 2024). "H19 has been shown to play an important role in the tumorigenicity and stemness of glioblastoma and may be a therapeutic target for the treatment of glioblastoma in the future." (PMID 36531217, 2022). "Stemness: H19 was highly expressed in glioblastoma stem cells (CD133+ cells) and promoted stemness." (PMID 34322395, 2021). "Furthermore, in glioblastoma, H19 reduced expression of Nkd1, which is a Wnt pathway inhibitor, via EZH2-mediated epigenetic regulations, and its overexpression increased angiogenesis in in-vitro investigations." (PMID 34322395, 2021). "H19 was highly upregulated in temozolomide-resistant U251 and M059J glioblastoma cells." (PMID 33806782, 2021). "H19 silencing has reduced viability, migratory potential, and invasiveness of glioblastoma cells." (PMID 34178658, 2021). "MALAT-1 and H19 are well-studied lncRNAs in developing temozolomide MDR in glioblastoma." (PMID 33806782, 2021). "The diagnostic power of lncRNAs SAMMSON, HOTAIR, MALAT1, H19, and LINR-ROR has been assessed in serum or tissue samples of pateints with glioblastoma revealing the best results for the first two mentioned lncRNAs based on the high values of the area under the reciver operating characteristic curves." (PMID 33634032, 2020). "H19 enhances glioblastoma cell invasion, neurosphere formation, tumor growth and angiogenesis." (PMID 33634032, 2020). "Sponging of let-7 by H19 has also been described in glioblastoma." (PMID 33291403, 2020). "In our recent work, where we compared gene expression in glioblastoma tissues to peritumoral regions of the same patients, we observed that, while H19 was clearly overexpressed in tumors, the opposite was true for NKD1 (Log2FC peri vs tumor = 1.22, p = 0.0086)." (PMID 29643989, 2018). "Indeed, we showed that H19 binds EZH2 in glioblastoma cells, and that EZH2 binding to NKD1 and other promoters is impaired by H19 silencing." (PMID 29643989, 2018). "Our recent serial analysis of gene expression (SAGE) profiling of glioblastoma tissues showed that H19 is overexpressed in tumor samples from short-term survivors compared to healthy white matter, but notably also in the same samples when compared to tumor tissues from long-term survivors." (PMID 29643989, 2018). "As the Wnt pathway is strongly involved in glioblastoma, we hypothesized that H19 might play the same role in glioblastoma cells." (PMID 29643989, 2018). "We now show for the first time that H19 can regulate NKD1 expression in glioblastoma cells, and we suggest that NKD1 inhibition may be one of the ways through which H19 participates to glioblastoma growth." (PMID 29643989, 2018). "Furthermore, increased H19 promotes the invasion, angiogenesis, stemness, and tumorigenicity of glioblastoma cells." (PMID 29795132, 2018). "However, recent studies showed that H19 acts as an oncogene by promoting cell proliferation, migration, invasion, and metastasis in various malignancies including glioblastoma." (PMID 29636074, 2018). "Here we, hypothesyze that in glioblastoma H19 exerts its function through the interaction with the catalytic subunit of the PRC2 complex, EZH2." (PMID 29643989, 2018). "Hif-1α also positively correlates with H19 in human glioblastoma samples depending on PTEN status." (PMID 28327666, 2017). "In summary, our results uncover the mechanisms that stimulate H19 expression under hypoxia to promote malignant effects in glioblastomas and suggest H19 might be a promising therapeutic target." (PMID 28327666, 2017).
glioblastoma (continued). "H19 expression is elevated in many human tumors including glioblastomas, suggesting an oncogenic role for the long noncoding RNA; yet the upregulation of H19 in glioblastomas remains unclear." (PMID 28327666, 2017). "The oncogenic effects of H19 in glioblastomas were explored by public database of expression." (PMID 28327666, 2017). "Moreover, H19 expression upregulated β-catenin expression via binding and inhibiting miR-181d, which negatively regulated β-catenin mRNA, thereby contributing to H19 oncogenic functions in glioblastomas." (PMID 28327666, 2017). "More recently, in glioblastoma, hypoxia-induced H19 upregulation was reported to drive an aggressive phenotype by absorbing miR-181d and aborting the miR-181d-mediated repression on β-catenin, an oncogenic factor associated with EMT (epithelial-mesenchymal transition)." (PMID 28789687, 2017). "Interestingly, H19 expression remained low after 48 h culture under hypoxia in Ln229 glioblastoma cells." (PMID 28327666, 2017). "Finally, we showed that the mechanism through which H19 regulates glioblastoma migration and invasion involved β-catenin expression." (PMID 28327666, 2017). "We found that decreasing PTEN protein levels could maintain Hif-1α expression and elevate H19 RNA levels under hypoxia in Ln229 glioblastoma cells, and vice versa in U87 cells." (PMID 28327666, 2017). "For example, lncRNA H19 promotes oncogenic effects in glioblastoma." (PMID 29296221, 2017). "It is well known that lncRNA H19 is expressed aberrantly in a wide range of tumours, promoting growth and dissemination (see review); moreover, in different tumours, e.g., prostate cancer and glioblastoma, H19 expression was found significantly upregulated in hypoxia." (PMID 33673376, 2021). "HOTAIR could promote glioblastoma cell cycle progression; FOXM1-AS could enhance self-renewal and tumorigenesis of glioblastoma stem-like cells; H19 could promote glioblastoma cell invasion, angiogenesis, and tube formation; MALAT1 could decrease the sensitivity of glioblastoma cells to TMZ." (PMID 34759954, 2021). "Moreover, they found that HIF-1α may promote H19 expression by both directly binding to the H19 promoter and indirectly through SP1-mediated H19 transcriptional activation under hypoxia in glioblastoma cells." (PMID 33673376, 2021). "Finally, the potential tumorigenicity of glioblastoma cells may also be affected by recruitment of EZH2 (a subunit of the Polycomb Repressive Complex 2) to the NKD1 promoter by H19, with its repression positively contributing to glioblastoma tumorigenicity." (PMID 32283739, 2020). "Upon knock-down of H19 both cell lines showed an increase in Nkd1 expression, at the mRNA as well as at the protein level, suggesting that this lncRNA might affect Nkd1 expression in glioblastoma cells." (PMID 29643989, 2018). "Additionally, the contributions of several lncRNAs, such as Hox transcript antisense intergenic RNA, H19 and Colorectal neoplasia differentially expressed, previously reported to be involved in other pathogenesis and processes to the oncogenesis of glioblastoma are currently addressed." (PMID 28293170, 2017). "Therefore, H19 participates in hypoxia-driven migration and invasion in glioblastoma cells." (PMID 28327666, 2017). "A recent study has shown that the long non-coding RNA (LncRNA) H19 encodes an immune-related protein, H19-IRP, which promotes immunosuppression in glioblastoma multiforme (GBM) by binding to and activating the transcription of the CCL2 and galactaglutinin-9 promoters." (PMID 40297808, 2025). "Hence, H19 may be a valuable therapeutic target in glioblastoma." (PMID 39015773, 2024). "The following lncRNAs engaged in glioblastoma therapy resistance were selected: MALAT1, CASC2, H19, TUSC7, XIST, RP11-838N2.4, DLX6-AS1, GLIDR, MIR210HG, SOX2-OT." (PMID 33245508, 2022).
glioblastoma (continued). "Alternatively, in glioblastoma (GBM), specific protein 1 (SP1) plays a crucial intermediary role in HIF-1α-mediated H19 expression via binding GC-boxes in the H19 promoter." (PMID 35842651, 2022). "Through gene expression analysis between glioblastoma LN229 cell line and LN229/TMZR, H19 shows a lower expression in resistant cell line (GSE113510)." (PMID 36246634, 2022). "For example, H19 is significantly overexpressed in CD133+ glioblastoma cells, which increases neurosphere formation in glioblastoma cells." (PMID 34539892, 2021). "Knockdown of H19 via siRNA resulted in increased TMZ-induced apoptosis rate in U87MG and U251 cell lines in glioblastoma." (PMID 34322395, 2021). "Since high levels of H19 have a markedly poor outcome in glioblastomas, glioblastoma cells cultured under hypoxia showed a stronger migration and invasion capacity than cells cultured under normoxia, these enhanced capacities could be relieved by knocking down H19." (PMID 28327666, 2017). "H19 was shown to have relatively high and low expression levels in CD133+ and CD133− glioblastoma cells, respectively." (PMID 27229531, 2016). "In addition, H19 regulates High Mobility Group AT-Hook 2 (HMGA2) expression and microRNAs, both of which enhance the mesenchymal transition of glioblastoma and self-renewal of GSCs." (PMID 39015773, 2024). "In glioblastoma cell lines under hypoxia, HIF-1α can stimulate the expression of H19 by directly binding to the H19 promoter, or by up-regulating the expression of specific protein 1 (SP1) protein and then binding to the H19 promoter to promote the expression of H19." (PMID 36139386, 2022). "Also, the miR-675-5p, which is embedded in hypoxia-induced long non-coding RNA H19, is required to sustain the activity of HIF-1α at least in Glioblastoma and Colorectal cancer models." (PMID 33673376, 2021). "In addition, growing evidence indicates that lncRNAs have various roles in resistance to glioblastoma therapies (e.g., MALAT1, H19) and in glioblastoma progression (e.g., CRNDE, HOTAIRM1, ASLNC22381, ASLNC20819)." (PMID 32650527, 2020). "Notably, expressions of oncogenic lncRNAs lnc-TALC, LncSBF2-AS1, MALAT1, TP73-AS1, and H19 as well as expression of tumor suppressor lncRNAs AC003092.1, TUSC7, and RP11-838N2.4 have been shown to alter this phenotype in glioblastoma cells." (PMID 33634032, 2020). "However, expression of H19 is significantly increased in CD133+ cells, glioblastoma tissue, and high tumor grade, and is also negatively associated with patient survival." (PMID 32650527, 2020). "Furthermore, Hif-1α upregulated specific protein 1 (SP1) expression in glioblastomas cells in vitro and in vivo, and SP1 also strongly interacted with the H19 promoter to promote H19 expression under hypoxia." (PMID 28327666, 2017). "In this study, we demonstrated that the mechanism of H19 induction under hypoxia is partly accounted for by Hif-1α directly binding to the H19 promoter, a process that requires specific protein 1 (SP1) to be activated by Hif-1α, which enhances H19 transcriptional activation in glioblastoma cells." (PMID 28327666, 2017). "Furthermore, knockdown of H19 has been shown to downregulate the stem cell-related genes SOX2, OCT4, and NANOG, as well as other CSC markers in glioblastoma and embryonic carcinoma cell lines." (PMID 28872613, 2017). "CircRNA targeting H19 immune-related protein (H19-IRP) induces cytotoxic T-lymphocyte (CTL) responses and suppresses glioblastoma (GBM) growth." (PMID 40710359, 2025). "Up-regulation of a number of oncogenic lncRNAs such as H19, MALAT1, SNHGs, MIAT, UCA, HIF1A-AS2 and XIST in addition to down-regulation of other tumor suppressor lncRNAs namely GAS5, RNCR3 and NBAT1 indicate the role of these lncRNAs in the pathogenesis of glioblastoma." (PMID 33634032, 2020).
atherosclerosis (64 papers, 2016 to 2026). A disease characterized by the build-up of fatty material and calcium deposition in the arterial wall resulting in partial or complete occlusion of the arterial lumen. "lncRNA H19 is associated with atherosclerosis risk, with polymorphisms in H19 linked to this condition in a Chinese population." (PMID 39135912, 2024). "In conclusion, this research depicted a pathogenic function of lncRNA H19 in promoting the development of atherosclerosis and revealed a new mechanism for ANGPTL4 modulation." (PMID 34820432, 2021). "H19 is low-expressed under normal circumstances, but some scholars have found that it is high-expressed in patients with atherosclerosis and increased risk of coronary heart disease." (PMID 33403385, 2021). "In atherosclerosis, another subtype of stroke, H19 promoting ACP5 protein and increased the risk of ischemic stroke." (PMID 33193379, 2020). "Long non-coding RNA H19 was significantly upregulated in the serum of patients with atherosclerosis and those with a high risk of coronary artery disease in a Chinese population." (PMID 32082313, 2020). "H19 was one of the first lncRNAs to be discovered and has been implicated in diseases, such as atherosclerosis, though its non-coding nature was only recognized years after the H19 cDNA was first cloned." (PMID 33329688, 2020). "Increasing evidence has shown that H19 is involved in the process of hypertension and atherosclerosis pathology, which are important risk factors for the development of IA." (PMID 31275455, 2019). "Several lncRNAs, including STEEL, LASSIE, SENCR, LEENE, MALAT1, and H19, have been implicated in the development and progression of atherosclerosis through their involvement in biological processes such as inflammatory response, cholesterol metabolism, and pyroptosis." (PMID 39432244, 2024). "In addition, H19 was shown up-regulated in the blood and aortic root of atherosclerosis-prone apolipoprotein E-deficient (ApoE−/−) mice fed with western diet as compared with the control C57BL/6 mice on chow diet." (PMID 35946958, 2022). "Recent studies have identified H19 as a well-known lncRNA associated with atherosclerosis." (PMID 34421622, 2021). "After preliminarily verifying that m6A modification promoted HAEC pyroptosis in atherosclerosis, we identified the main lncRNA molecule affected by m6A modification as H19." (PMID 39432244, 2024). "In contrast with the atherosclerosis+si‐METTL3+vector group, serum TC, TG, and LDL‐C levels in mice in the atherosclerosis+si‐METTL3+H19 group significantly increased (p < .05), while the HDL‐C level markedly decreased." (PMID 39432244, 2024). "METTL3‐mediated m6A modification regulated H19 expression, thereby aggravating atherosclerosis by activating pyroptosis." (PMID 39432244, 2024). "Compared with the atherosclerosis+si‐METTL3+vector group, the ratio of plaque to the vascular area in the aortas of mice in the atherosclerosis+si‐METTL3+H19 group was significantly increased (p < .05)." (PMID 39432244, 2024). "Briefly, H19 overexpression significantly aggravated atherosclerosis alleviated by METTL3 knockdown." (PMID 39432244, 2024). "Overexpression of H19 reversed these effects, indicating METTL3's role in promoting atherosclerosis by stabilizing H19 through m6A modification." (PMID 39432244, 2024). "We analyzed the levels of m6A‐related writer proteins in cell and animal models of atherosclerosis and identified lncRNA H19 (H19) as a primary target of m6A modification." (PMID 39432244, 2024). "In summary, H19 is the main target lncRNA molecule of METTL3 mediated‐m6A modification in the pathological process of atherosclerosis." (PMID 39432244, 2024). "Subsequent in vivo experiments demonstrated that reducing METTL3 expression effectively mitigated atherosclerosis progression in mice, while H19 upregulation exacerbated the condition." (PMID 39432244, 2024).